IRS1 (insulin receptor substrate 1)
Diseases named in the same sentence as IRS1 in open-access papers (continued):
Sharing a sentence is not in itself a finding about the gene and the disease.
preeclampsia (3 papers, 2011 to 2018). Preeclampsia is a hypertensive disorder of pregnancy that is characterized by new-onset hypertension with proteinuria presenting after 20 weeks of gestation, and depending on mild or severe forms may initially present with severe headache, visual disturbances, and hyperreflexia. "This may be explained by IRS-1 and IRS-2 inhibition due to serine-phosphorylation and subsequent impairment of downstream insulin signaling in preeclampsia." (PMID 27738431, 2016).
Sepsis (3 papers, 2017 to 2024). Sepsis is defined as life-threatening organ dysfunction caused by a dysregulated host response to infection. "We hypothesize that sepsis attenuates insulin-stimulated tyrosine phosphorylation of either IRβ, IRS-1 or IRS-2." (PMID 37550630, 2023). "Conversely, our demonstration that CLP attenuated IRS-1/2 tyrosine phosphorylation indicates that CLP, and perhaps sepsis, are indeed states of insulin resistance." (PMID 37550630, 2023).
tendinopathy (3 papers, 2020 to 2022). "Most importantly, the expression of IRS1 and Nox4 was as predicted increased, especially in the abnormal cell proliferation zone, which validated that IRS1 and Nox4 are positively related to tendinopathy." (PMID 31065679, 2020). "Taken together, we deduced that miR-337-3p can be a therapeutic target of tendinopathy through downregulating chondro-osteogenic differentiation of rTDSCs by targeting IRS1 and Nox4 as elucidated in the schematic diagram." (PMID 31065679, 2020). "Our study indicated Nox4 and IRS1 as the therapeutic targets of tendinopathy; however, further research is needed to clarify the functional mechanism of Nox4 and IRS1 in chondro-osteogenesis in tendinopathy." (PMID 31065679, 2020). "Also the expression of miR-337-3p was also downregulated in the calcification tendon of tendinopathy patients, with increased IRS1 and Nox4 tested by real-time PCR." (PMID 31065679, 2020). "Furthermore, we tested the in situ expression of IRS1 and Nox4 in human tendinopathy samples." (PMID 31065679, 2020). "IRS1 and ERK-1/2 were once demonstrated to be activated in load-induced tenocyte in vivo under insulin-like growth factor 1 (IGF1) signaling during the pathogenesis of overused tendon disorders although no chondro-osteogenesis was observed." (PMID 31065679, 2020).
3-M syndrome (2 papers, 2015 to 2018). 3M syndrome is a primordial growth disorder characterized by low birth weight, reduced birth length, severe postnatal growth restriction, a spectrum of minor anomalies (including facial dysmorphism) and normal intelligence. "An intriguing recent finding is that Cul7-Fbw8 can degrade the insulin receptor substrate 1 (IRS-1) through Skp1-Fbw8-ROC1 (SCF complex), suggesting the mechanism of 3-M syndrome is related to IRS-123." (PMID 26423533, 2015).
acute coronary syndrome (2 papers, 2008 to 2011). Signs and symptoms related to acute ischemia of the myocardium secondary to coronary artery disease. "Moreover, acute coronary syndrome (ACS) has been linked through genome-wide association studies to the 2q36-q37.3 locus, which contains the Irs1 gene." (PMID 22347652, 2011). "Genome-wide studies suggest a link between acute coronary syndrome (ACS) and the 2q36-q37.3 locus, which encompasses the insulin receptor substrate-1 (Irs1) gene." (PMID 22347652, 2011).
acute lymphoblastic leukemia (2 papers, 2018 to 2020). Leukemia with an acute onset, characterized by the presence of lymphoblasts in the bone marrow and the peripheral blood. "A constitutive IRS1 and β-catenin protein interaction activated MYC expression in Acute Lymphoblastic Leukemia Cells." (PMID 32851100, 2020).
adenoma (2 papers, 2012 to 2017). A neoplasm arising from the epithelium. "Overexpression of IRS1, together with ß-catenin, InsRß, and IGF1R, in FAP-associated adenomas was in agreement with data reported for the Apc(Min/+) mouse model." (PMID 22558377, 2012). "IRS1 mRNA and protein resulted higher, relative to paired mucosa, in adenomas of familial adenomatous polyposis patients and in CRCs that overexpressed c-MYC, ß-catenin, InsRß, and IGF1R." (PMID 22558377, 2012). "In the two FAP cases, IRS1 markedly increased in the adenoma relative to mucosa, together with InsRß, IGF1Rß and ß-catenin, and IHC showed diffuse IRS1 in adenomas." (PMID 22558377, 2012). "Downregulated expression of miR-143 and miR-145 has been described to target multiple mRNAs related to the MAPK signaling pathway, including K-Ras, ERK5, IRS-1 (insulin receptor substrate 1), all of them involved in the transition of an early adenoma to advanced stages." (PMID 28573140, 2017).
allergic disease (2 papers, 2015 to 2018). An immune response that occurs following re-exposure to an innocuous antigen, and that requires the presence of existing antibodies against that antigen. "Substantial progress has been made over the past 28 years in understanding the contribution of 4PS (IRS1 or IRS2) to IL-4- and IL-13-stimulated responses in the context of allergic diseases, however, as noted throughout, there is still much work to be done." (PMID 29868002, 2018). "However, our current understanding of the relative roles of IRS1 and IRS2 in mediating and modulating allergic diseases is quite limited." (PMID 29868002, 2018).
Atrophy (2 papers, 2017 to 2024). Any weakening or degeneration, especially through lack of use. "Given that NFTs are known to be closely associated with atrophy, our findings collectively tie together IRS1 expression and post-translational phosphorylation, NFT pathology and atrophy." (PMID 28515688, 2017). "The Western blot analysis further confirmed that CMP could promote the activation of the IRS-1/Akt/S6K protein synthesis signaling pathway and decrease the expression of markers of muscle atrophy MuRF1 and Atrogin-1." (PMID 38397848, 2024).
Cerebral ischemia (2 papers, 2020 to 2021). Restriction of arterial blood supply to the brain associated with insufficient oxygenation to support the metabolic requirements of the tissue. "Upon examining the gastrocnemius muscles, cerebral ischemia caused a reduction in Akt phosphorylation and an increase in IRS1 phosphorylation at 307 serine residue, JNK phosphorylation, p38 phosphorylation, and TNFRI." (PMID 32492962, 2020). "We speculated that there was relatively little involvement of Fbxo40 in cerebral ischemia-associated hepatic and muscular insulin resistance because IRS1 content remained constant among the groups." (PMID 34943061, 2021). "There was a reduction in active IRS1-associated tyrosine phosphorylation and Akt phosphorylation, and an increase in inhibitory IRS1-associated serine phosphorylation in the gastrocnemius muscles following cerebral ischemia, and the changes were alleviated by AG490." (PMID 34943061, 2021). "Thus, the neuroprotective effects of insulin against cerebral ischemia may be to boost the IRS1/Akt-mediated neurotrophic activity." (PMID 32492962, 2020).
cholangiocarcinoma (2 papers, 2023 to 2024). A carcinoma that arises from the intrahepatic biliary tree (intrahepatic cholangiocarcinoma) or from the junction, or adjacent to the junction, of the right and left hepatic ducts (hilar cholangiocarcinoma). "Moreover, overexpression of IRS1 has been found to promote migration in cholangiocarcinoma and regulate invasion in pancreatic cells via both MAPK and PI3K signaling pathways." (PMID 38272982, 2024).
chondrosarcoma (2 papers, 2010 to 2016). A malignant cartilaginous matrix-producing mesenchymal neoplasm arising from the bone and soft tissue. "Mediators of IGF1R signalling are heterogeneously expressed and phosphorylated IRS1 was detected in 67 % of the tested chondrosarcoma cell lines, suggesting that IGF1R signalling is active in a subset of chondrosarcoma cell lines." (PMID 27418340, 2016). "Expression of mediators of IGF1R signalling and phosphorylation status of IRS1 was determined in chondrosarcoma cell lines by qRT-PCR and western blot." (PMID 27418340, 2016). "Leptin was shown to regulate the differentiation of the ATDC5 chondrogenic cell line through activation of ERK1/2, and to activate the IRS-1/PI3K/Akt pathway to induce migration of human chondrosarcoma cells." (PMID 20534145, 2010). "Furthermore, detection of phosphorylated IRS1 in two out of three chondrosarcoma cell lines demonstrates that the IGF pathway is active in a subset of chondrosarcoma cell lines." (PMID 27418340, 2016). "Heterogeneous expression of IGF1R, IR, IGF2R, IGF1, IGF2, IRS1 and IGFBP3 was seen, both at the mRNA and protein levels, in chondrosarcoma cell lines." (PMID 27418340, 2016).
colon adenoma (2 papers, 2017 to 2024). An adenoma that arises from the colon. "It has been reported that IRS-1 expression is increased in colon adenomas compared with normal colon epithelium." (PMID 28414818, 2017).
corticobasal degeneration (2 papers, 2019 to 2021). "Yarchoan and colleagues reported that BIR was related to IRS1-pS616 and IRS1-pS312 expression in LOAD and brain tauopathies, including Pick’s disease, corticobasal degeneration, and progressive supranuclear palsy." (PMID 34577590, 2021).
Endotoxemia (2 papers, 2010 to 2016). "In the present paper we now provide evidence that iNOS-linked IRS-1 tyrosine nitration also underlies skeletal muscle IR in the acute inflammatory setting of endotoxemia." (PMID 21206533, 2010). "Endotoxemia also subsequently decreases phosphorylation of insulin receptor substrate-1 (IRS-1) and protein kinase B (Akt), finally leading to dysfunction of glucose transport." (PMID 26799617, 2016). "Herein, using both in vivo and in vitro models of endotoxemia we delineated the important role that iNOS-dependent tyrosine nitration of the proximal insulin signaling intermediate, IRS-1, plays in endotoxemia-induced skeletal muscle IR." (PMID 21206533, 2010).
Huntington disease (2 papers, 2020 to 2023). Huntington disease (HD) is a rare neurodegenerative disorder of the central nervous system characterized by unwanted choreatic movements, behavioral and psychiatric disturbances and dementia. "The inhibitor-induced a reduction of p-IGF-1R and degradation of the IR substrates 1 and 2 (IRS1/2) leading to the enhanced stress resistance and protection against Aβ and polyQ40 proteotoxicity, AD and Huntington’s disease-associated proteins, respectively." (PMID 32719587, 2020).
hypothyroidism (2 papers, 2018 to 2023). Abnormally low levels of thyroid hormone. "Overall, the increase of IRS1 phosphorylation of Ser302 is not in agreement with the detected hypothyroidism." (PMID 37298533, 2023). "Furthermore, expression levels of GLUT4, IRS-1, and IRC proteins were decreased in adult female rats with hypothyroidism than normal group (P<0.05)." (PMID 29784871, 2018).
infertile (2 papers, 2022 to 2025). "There was a statistically significant relationship between the expressions of INSR and IRS-1 genes in theendometrial tissue of the infertile women compared with the fertile women (P=0.002 and P=0.008, respectively)." (PMID 36273315, 2022). "Healthy infertile subjects showed 21.35times more expression of the INSR gene (P<0.0001, 95%CI: 0.230-0.604) than the infertile ones with diabetesand 16.82 times more expression for the IRS-1 gene(P<0.0001, 95% CI: 0.091-0.152)." (PMID 36273315, 2022). "In obese fertile women, expression ofboth genes decreased significantly, but the infertile groupshowed a slight expression decrease in the INSR gene andan increased expression in the IRS-1 gene." (PMID 36273315, 2022). "In comparisonwith the fertile group, the expression of the INSR genewas 2.95 times (P=0.005, 95% CI: 0.397-4.010) higherand the IRS-1 gene was 2.92 times (P<0.0001, 95% CI:0.204-1.719) higher than that of the infertile group withthe age of ≤30." (PMID 36273315, 2022). "In the fertile group, the expression of the INSR gene was2.61 times higher (P=0.002, 95% CI: 0.639-2.622) andthe IRS-1 gene was 2.87 times higher (P=0.008, 95% CI:0.177-1.137) than the infertile group." (PMID 36273315, 2022). "In this study, the expression levels of insulin receptor (INSR) and insulin receptor substrates-1 (IRS-1)genes in endometrial tissue of infertile women and fertile women with miscarriage in less than twenty weeks gestationfor unknown reasons were evaluated." (PMID 36273315, 2022). "Comparison of BMI ≤25 in the fertile womencompared to the infertile women showed that the expressionof the INSR gene was 10.07 times (P=0.002, 95% CI: 0.251-5.161) and IRS-1 gene was 4.31 times (P<0.0001, 95% CI:0.533-2.270) higher." (PMID 36273315, 2022). "The infertile group had lowerexpression of the INSR and IRS-1 genes in uterinetissue compared to the fertile group." (PMID 36273315, 2022). "Also, fertile and infertile persons atBMI >25 had 1.78 times (P=0.042, 95% CI: 0.214-2.026)more expression of the INSR gene and 2.19 times (P<0.0001,95% CI: 0.069-0.812) more expression of the IRS-1 gene." (PMID 36273315, 2022).
leiomyosarcoma (2 papers, 2002 to 2021). An uncommon, aggressive malignant smooth muscle neoplasm, usually occurring in post-menopausal women. "Discussion: Our findings tend to exclude that the malignancy displayed by uterine leiomyosarcomas might be directly linkedto the activation of distinct IRS-1- or IRS-2-dependent pathways." (PMID 18521338, 2002).
mesothelioma (2 papers, 2012 to 2021). A usually malignant and aggressive neoplasm of the mesothelium which is often associated with exposure to asbestos. "Interestingly, the low citrate levels observed in malignant mesothelioma cells can be restored by microRNA-126 overexpression, a treatment which efficiently suppresses tumor growth, and inactivates ACLY and the insulin receptor substrate-1 (IRS-1)/Akt pathway." (PMID 34205414, 2021).
muscular atrophy (2 papers, 2017 to 2024). The loss of muscle tissue due to inactivity or disease. "Overall, the present study provides the first evidence for the role of CMP in H2O2-induced C2C12 muscular atrophy cells, and the underlying mechanism may be associated with activating the IRS-1/Akt/S6K pathway to promote protein synthesis by reducing insulin resistance and mitochondrial dysfunction." (PMID 38397848, 2024). "It has been reported that, in the galactose injection induced aged mice model, low activated IRS1 or Akt and high activated FoxO1 associated with muscular atrophy could be improved by exercise remission, through the way of activated IRS1 and Akt, facilitated by the phosphorylation of FoxO1." (PMID 29271915, 2017).
Osteopenia (2 papers, 2015 to 2017). Osteopenia is a term to define bone density that is not normal but also not as low as osteoporosis. "In rodents, including insulin receptor substrate-1 (IRS-1) and IRS-2 knock-out mice and streptozotocin-induced diabetic mice, studies have shown severe osteopenia, decreased bone formation, and severe growth retardation, respectively." (PMID 28630427, 2017). "Furthermore, osteoblast lacking IRS1 impairs osteoblast proliferation and differentiation, inducing osteoclastogensis, and results in low turnover osteopenia." (PMID 25978640, 2015).
prediabetes (2 papers, 2015 to 2022). "This cross-sectional study aimed to investigate the independent risk factors for prediabetes, considering the contribution of genetic factors (TCF7L2-rs7903146, IRS1-rs1801278, INSR-rs3745551, CDKN2A-rs10811661, and FTO-rs9939609), socio-economic status, and lifestyle factors." (PMID 26334876, 2015). "Therefore, the study was designed to investigate both genetic (TCF7L2-rs7903146, IRS1-rs1801278, INSR-rs3745551, CDKN2A-rs10811661, and FTO-rs9939609) and environmental factors for prediabetes in a Vietnamese population." (PMID 26334876, 2015).
prostate tumor (2 papers, 2017 to 2025). "miR-384 has suppressive effects on tumor cell proliferation through the direct inhibition of IRS1 expression, and contributes to aberrant Runx expression in prostate tumors." (PMID 28400721, 2017). "In addition, both in vitro and in vivo findings revealed that the deletion of miR-21 inhibits prostate tumor development by disrupting the IRS1/SREBP-1 signaling cascade." (PMID 41465187, 2025).
tauopathies (2 papers, 2019 to 2022). "The analysis of extreme values for p-IRS-1(Ser616) and p-Tau(Thr231) in our study confirms that tauopathy and amyloidopathy both may be induced by metabolic disturbances induced by the WD through independent cellular processes." (PMID 35563135, 2022).
viral infection (2 papers, 2015 to 2021). "In addition to the PI3K/Akt pathway, E1A can also associate with the insulin receptor substrate (IRS-1) to increase Akt phosphorylation, which contributes to adenovirus-transformed phenotypes and modulates viral infection in an Akt-dependent manner." (PMID 26515462, 2015). "We show that the viral infection activates an integrated stress response, including activations of serine kinases such as PKR and PERK, which induce IRS-1 serine phosphorylation and insulin resistance." (PMID 33648564, 2021). "Moreover, we show that the viral infection activates an ISR, including activations of serine kinases such as PKR and PERK, which will induce IRS-1 serine phosphorylation and insulin resistance." (PMID 33648564, 2021).
Wilms tumor (2 papers, 2013 to 2021). An embryonal neoplasm characterized by the presence of epithelial, mesenchymal, and blastema components. "Increasing evidence has shown that miR-370 regulates a number of target genes, including Wilms tumor gene on the X chromosome, insulin receptor substrate 1, Forkhead box protein O1 and FoxM1 in AML by our group." (PMID 24148180, 2013).
Acidosis (1 paper, 2015). Abnormal acid accumulation or depletion of base. "Specifically, extracellular acidosis was associated with an increase in the amount of PI3-K p85 subunit protein which decreased IRS-1-associated PI3-K activity, resulting in a reduction in the phosphorylation (i.e., activation) of Akt (protein kinase B)." (PMID 26656911, 2015).
Adrenal Hyperandrogenism (1 paper, 2021). Excessive secretion of the androgen hormones dehydroepiandrosterone (DHEA), DHEA sulfate, and androstenedione, from the adrenal gland. "For example, studies investigating the combination of CYP21A2 gene variations together with the G972R variant of the insulin receptor substrate-1 gene, which is more common in PCOS patients with severe adrenal hyperandrogenism, have shown interesting results." (PMID 34071512, 2021).
amyotrophic lateral sclerosis (1 paper, 2023). Amyotrophic lateral sclerosis (ALS) is a neurodegenerative disease characterized by progressive muscular paralysis reflecting degeneration of motor neurons in the primary motor cortex, corticospinal tracts, brainstem and spinal cord. "The amyotrophic lateral sclerosis (ALS)-derived VAPB P56S mutant also impaired IRS-1 stability by interfering with the ER-tethering of IRS-1." (PMID 37528084, 2023).
Anorexia (1 paper, 2020). Lack of desire to eat (loss of appetite). "After feeding fish carbohydrate-rich diets, carbohydrates could be enzymatically catalyzed to produce UDP-N-acetylglucosamine, which inhibits the expression of irs1 gene in the mandarin fish with anorexia." (PMID 32636801, 2020). "In addition, the activation of mtor signaling could also inhibit the expression of irs1 gene in the mandarin fish with anorexia." (PMID 32636801, 2020).